BRCA1 (BRCA1 DNA repair associated)
Diseases named in the same sentence as BRCA1 in open-access papers (continued):
Sharing a sentence is not in itself a finding about the gene and the disease.
cancer (continued). "The Cancer Control Supplemental survey used for this analysis focused on BRCA1/2-related cancers among women; however, BRCA1/2 mutations can also occur in men and recent results have demonstrated a gender gap in genetic testing." (PMID 31083288, 2019). "Taken together, our findings support the importance of genetic changes in BER pathway genes as modifiers of cancer susceptibility for BRCA1 and BRCA2 mutation carriers." (PMID 30747491, 2019). "Our report is to our knowledge the first report focusing cancer incidence in fertile ages in prospectively detected carriers of path_BRCA1 variants in order to consider why some path_BRCA1 variants become more frequent than others." (PMID 30678073, 2019). "In women, due to the combination of a high prevalence of cancers at a young age, and cardiovascular diseases at an older age, the effect of BRCA1&2-mutations on cardiovascular morbidity and mortality is difficult to evaluate." (PMID 31489114, 2019). "Deficiency of BRCA1/2 proteins results in carcinomas with a diminished capacity to repair DNA and, presumably, decreased ability to repair DNA breaks caused by chemotherapy." (PMID 31771539, 2019). "Carcinomas from patients with TNBC from patients with pathogenic BRCA1/BRCA2 mutations have demonstrated unique sensitivity to platinum agents in both the neoadjuvant and adjuvant settings." (PMID 31379942, 2019). "Cancers that arise in individuals with a germline mutation in BRCA1/2, frequently acquire a somatic loss-of-function aberration in the corresponding wild-type BRCA allele, leading to HR repair deficiency." (PMID 30428574, 2018). "Third, we selected high-risk cases with genetic burdens using the similar indications as BRCA1/2 mutation test: age of onset, family history, history of other malignancy, and bilateral cancers." (PMID 30323354, 2018). "The BRAT1 protein participates in DNA damage responses, cell growth, and apoptosis by interacting with the tumor-suppressor protein BRCA1 (breast cancer 1) and the ATM protein (ataxia telangiectasia mutated) in humans." (PMID 30093865, 2018). "To investigate the relationship between BRCA1 SNPs and cancer risk, we conducted this meta-analysis." (PMID 29492227, 2018). "An overall test of association for men and women together showed a statistically significant association between BRCA1/2 mutations and increased non-cancer mortality, complementing our data." (PMID 29662617, 2018). "Mutations in HR genes (e.g. BRCA1 and BRCA2) and their epigenetic status (e.g. BRCA1 silencing) have been linked to an increased risk of developing a variety of cancers." (PMID 29986057, 2018). "PARP1 inhibitors are used in cancer therapies in the setting of BRCA1 (breast cancer type 1 susceptibility protein) or BRCA2 (breast cancer type 2 susceptibility protein) loss (olaparib and rucaparib approved by FDA in patients with HR dysfunction)." (PMID 29306194, 2018). "Formalin-fixed paraffin-embedded cancer tissue can undergo testing within a routine molecular-diagnostic setting as a clinical BRCA1/2 mutation screening strategy." (PMID 29453630, 2018). "This distribution is similar to that observed in patients with one primary cancer, in whom pathogenic variants in BRCA1 (35.0%), BRCA2 (23.1%), and the mismatch repair genes (15.4%) accounted for almost three-quarters of deleterious mutations." (PMID 30093976, 2018). "In fact, low BRCA1/2 mRNA-expression in BRCA1-wildtype cancers was associated with fully platinum-sensitivedisease and high expression was evidenced in platinum-refractory disease." (PMID 30111871, 2018). "Here we report on the progress of the GEMO study, the characteristics of the 5,303 actual participants and the prevalence and spectrum of BRCA1/2 cancer-associated variants identified so far." (PMID 30430080, 2018). "This increase in genetic testing also correlates with the worldwide introduction of PARP inhibitors for the treatment of cancers with mutations in BRCA1/2." (PMID 30040829, 2018).
cancer (continued). "Our first aim was to evaluate family history of cancer and to detect BRCA1 and BRCA2 mutations in very young Brazilian patients." (PMID 29854292, 2018). "Recently, the acquisition of PARPi-resistance has been investigated in BRCA1-deficient cancer cells, and has also been observed in RAD51C and RAD51D patients." (PMID 30551670, 2018). "Considering the limited number of cancer types in and the sample size of this meta-analysis, more studies including various types of cancer are needed to investigate the association between BRCA1 polymorphisms and cancer risk in the future." (PMID 29492227, 2018). "Multi-gene panel testing identified deleterious mutations in genes other than BRCA1/2 or mismatch repair protein genes in 10.4% of patients with single primary cancers and in 13.7% of patients with multiple primary cancers." (PMID 30093976, 2018). "The HRR protein BRCA1 is frequently mutated in cancer and was described as a biomarker in breast and ovarian cancer." (PMID 29562639, 2018). "With respect to mostly 60% of BRCA1 mutation carries displaying a TNBC phenotype, BRCA1 related cancers are closely correlated with TNBC." (PMID 30007403, 2018). "In this context, BRCA1 gene mutation that causes predisposition to hereditary breast and ovarian cancers has also been reported to increase the metastatic ability of cancer cells." (PMID 30224826, 2018). "The close link between BRCA and PARP1 was highlighted in 2005 when two research groups independently discovered that PARP inhibition induces synthetic lethality in mutated BRCA1 or BRCA2 cancers." (PMID 30518089, 2018). "BRCA1 was especially associated with malignant tumors (reduced nuclear expression), which was also confirmed in previous studies." (PMID 30373614, 2018). "Prevalence of protein truncating variants (PTVs) in eight non‐BRCA1/2 cancer predisposition genes in 5589 BC index patients compared with control datasets (ExAC, FLOSSIES, and GMCs)." (PMID 29522266, 2018). "This study represents one of the largest retrospective studies of cancers in male BRCA1/2 mutation carriers, consisting of 102 male patients who were identified in a clinical cohort." (PMID 29433453, 2018). "Detection of disease-associated variants in the BRCA1 and BRCA2 (BRCA1/2) genes allows for cancer prevention and early diagnosis in high-risk individuals." (PMID 30646163, 2018). "In summary, this makes saliva a well-suited source for a variety of studies and especially for the detection of cancer biomarkers (e.g., specific germline mutations in BRCA1 and BRCA2) during screening procedures." (PMID 29703267, 2018). "Among the 23 deaths, the cause of death was determined to be BRCA1/2-associated cancer in 9 people (39.1%), unrelated to BRCA1/2 in 11 (47.8%), and indeterminate in 3 (13.0%)." (PMID 30646163, 2018). "The high 50% rate of BRCA1/2 mutations detected in 58 patients with both cancers diagnosis is in line with other studies on similar patients, although in smaller numbers, such as the Japanese study with 3 cases, all with a mutation detected." (PMID 30103829, 2018). "Most of our high-risk patients are carriers of BRCA1/2 pathogenic variants and adhered to a surveillance plan that allowed for cancer detection and treatment in 14 patients." (PMID 29456621, 2018). "One of the most intriguing outcomes of our study is that VEGF-A overexpression in pOC has been most frequently found among patients with a cancer somatic mutation of BRCA1/2 genes." (PMID 29955134, 2018). "Of note, the combination of taxanes with anthracyclines in a neoadjuvant setting was associated with better outcomes in the BRCA1-associated cancer." (PMID 30544963, 2018).
cancer (continued). "Here, we established the prevalence and spectrum of the germline pathogenic variants in the BRCA1/2 and 23 other cancer-related genes in a large Polish population of 333 unselected OC cases." (PMID 30441849, 2018). "For instance, tumours deficient for BRCA1/2 genes are highly sensitive to interstrand DNA crosslinking agents, such as cisplatin and carboplatin, and to a new class of anti-cancer agents called poly (ADP-ribose) polymerase (PARP) inhibitors." (PMID 28967905, 2018). "Out of the 23 patients with a personal history of HBOC-associated cancer who were found to carry a DV, only 35% (n = 8) had a DV in BRCA1/2, while the majority of these positive cases had a DV in non-BRCA genes." (PMID 29308099, 2018). "Studies regarding rs1799966, rs1799950, and rs16941 are similarly inconsistent, so we performed a meta-analysis to more precisely determine the association between BRCA1 polymorphisms and cancer risk." (PMID 29492227, 2018). "Inhibition of poly(ADP-ribose) polymerase (PARP) activity induces synthetic lethality in mutated BRCA1/2 cancers by selectively targeting tumor cells that fail to repair DNA double strand breaks (DSBs)." (PMID 30518089, 2018). "53BP1-dependent NHEJ is also problematic in BRCA1-deficient cancers, where it mediates chromosomal rearrangements that drive oncogenesis." (PMID 30559443, 2018). "This was mainly achieved by blocking the BER pathway by small molecule inhibitors against PARP in BRCA1/2-mutated cancers." (PMID 29459887, 2018). "Disrupted heterochromatin silencing is reported in BRCA1-deficient mouse brains, fibroblasts, mammary glands, and human cancer cells." (PMID 30558184, 2018). "In cancer patients, loss of BRCA1 function in tumor tissue has been associated with an increased sensitivity to platinum agents and to poly-(ADP-ribose) polymerase (PARP) inhibitors." (PMID 29996917, 2018). "This suggests that RDGVs in NSD1 are causally implicated in ~0.72% of cancers, a similar magnitude of effect as we observe for the well-known cancer predisposition genes BRCA1 (0.64%) and ATM (0.68%)." (PMID 29973584, 2018). "MiRNAs have diverse roles in cancer, including effecting DNA damage and have previously been linked to BRCA1 associated tumours." (PMID 30323900, 2018). "Cancers arising in carriers of BRCA1/2 germ-line mutation demonstrate an elegant therapeutic window." (PMID 30211169, 2018). "Several gene modifications including BRCA1 mutations in the cancer cells facilitate cancer progression and metastasis." (PMID 30224826, 2018). "Gene expression signatures present in germline BRCA1 mutations were also observed in BRCA1-methylated cancers." (PMID 30133561, 2018). "Only 5 to 10 % of all types of cancer are basically caused by inborn cancer predisposition such as the so-called familial breast cancer subtype known to be related to the BRCA1 and BRCA2 mutations." (PMID 30092754, 2018). "Cancer-associated HR mutations are commonly found in BRCA1 and BRCA2, and can be both germline and somatic." (PMID 30551670, 2018). "This concept has been harnessed in cancer therapy by the development of PARP inhibitors that selectively inhibit survival of cancer cells carrying mutations in homologous recombination repair genes, such as BRCA1 or BRCA2." (PMID 29983885, 2018). "This study describes the unique cancer characteristics of male BRCA1/2 mutation carriers at our institution." (PMID 29433453, 2018). "For example, carriers of pathogenic mutations in BRCA1/2 have both increased cancer risk and molecular evidence of homologous recombination deficiency in their tumors." (PMID 30217226, 2018).
cancer (continued). "Very promising biomarkers are miRNAs, cancer stem cells, and circulating tumor cells, as well as mutations of the breast cancer 1 gene (BRCA1) and breast cancer 2 gene (BRCA2)." (PMID 30373614, 2018). "One of the most common cancer related mutations found in BRCA1 is the 5382insC, reported to have originated from a common European ancestor about 400–500 years ago." (PMID 29459887, 2018). "Men with BRCA1/2 mutations are at increased risk for breast, prostate, pancreatic and other cancers." (PMID 29433453, 2018). "In the neXtProt Cancer variant portal, we have captured data for 466, i.e., 30% of the BRCA1 missense variants available in ClinVar." (PMID 29996917, 2018). "We conducted a population-based retrospective study in the province of British Columbia, Canada that included all patients visiting the Hereditary Cancer Program for genetic counselling for BRCA1 and BRCA2 mutation between 2001 and 2014." (PMID 29506471, 2018). "Many studies have reported that BRCA1 polymorphisms are associated with cancer risk, but the results remain controversial." (PMID 29492227, 2018). "Cancers harboring mutations in “BRCAness” genes, including BRCA1, BRCA2, ATM and PALB2, have been found to be sensitive to DNA crosslinking agents." (PMID 29515757, 2018). "Of the 103 BRCA1 founder pathogenic mutations, 53 (51%) were detected in healthy subjects and 50 (49%) were detected in cancer patients (Part A in S2 Fig)." (PMID 30040829, 2018). "Cancer-causing mutations in a tumor suppressor gene such as BRCA1 are expected to impair the protein’s biological activity." (PMID 30283497, 2018). "The purpose of this meta-analysis is to evaluate the relationship between BRCA1 polymorphisms (rs799917, rs1799950, rs1799966, or rs16941) and cancer risk." (PMID 29492227, 2018). "Although 18% of all BC cases tested by our group were found to be carriers of a BRCA1/2 pathogenic mutation, nearly 30% of our male referrals because of a cancer diagnosis (including multiple previous diagnoses) had an inconclusive test result." (PMID 29456621, 2018). "As the expression of BRCA1 cancer-related variants increased HR in yeast, we previously proposed the “yeast recombination assay” as reliable method to determine the functional impact of VUS." (PMID 30283497, 2018). "Serous cancer patients were significantly more likely to be BRCA1 and BRCA2 mutation positive with 21.3% testing positive for either BRCA1 or BRCA2 mutations compared to 7.5% of endometrioid or clear cell patients." (PMID 29506471, 2018). "This suggests that in the presence of CAFs, BRCA1 mutated cancer cells in aggressive cancers have the potential to induce tissue remodeling during tumor progression." (PMID 30224826, 2018). "The physical and functional interactions between BRCA1 and ERα provide a plausible molecular explanation for the preferential association of BRCA1 mutations with cancer risk in estrogen-responsive tissues/organs." (PMID 30558184, 2018). "Olaparib is an orally active PARP inhibitor that selectively kills cancer cells with deficient BRCA1 and BRCA 2, which encode proteins known to function in DNA repair through homologous recombination (HR)." (PMID 30647872, 2018). "Remarkably, the patients diagnosed with both cancers showed a 50% rate of mutation detection, again with similar distribution in both genes: 69% detected in BRCA1, 27.6% in BRCA2, and 3.4% in both genes." (PMID 30103829, 2018). "The initial report of an association between MLH1 and splicing mutations also associated other cancer related genes such as BRCA1, BRCA2, and NF1 with disrupted splicing." (PMID 29505604, 2018). "Age at sampling/onset of cancer and family history were taken as criteria for analysis of BRCA1- exon 2 mutations in Pakistan ethnicity." (PMID 30344568, 2018). "Somewhat paradoxically, cancer-predisposing mutations in BRCT domains significantly enhance the chromatin-unfolding activity of BRCA1." (PMID 30558184, 2018).
cancer (continued). "One article containing data regarding various types of cancer was treated as independent studies, and there were seven articles containing studies of various BRCA1 polymorphisms." (PMID 29492227, 2018). "Cancers arising in BRCA1/2 mutation carriers are often of high grade and more chromosomally unstable than their sporadic counterparts." (PMID 30211169, 2018). "There are no available clinical management guidelines for mutations in other predisposition genes except BRCA1/2, which urges future research to estimate better cancer risk and establish management guidelines for these mutations." (PMID 30007403, 2018). "We examined histology-based referral to the Hereditary Cancer Program following an educational prevention campaign recommending BRCA1 and BRCA2 mutation screening for all high-grade serous cancer patients." (PMID 29506471, 2018). "All these observations compelled us to consider the existence of a group of CAFs, with an altered phenotype (embedded among the primary CAFs), that is conditioned by BRCA1 mutated cancer cells." (PMID 30224826, 2018). "Only 17.2% of our GPs referred their patient with BRCA1/2 mutation to the oncogenetics consultation, but most GPs looked for a family history of cancer during the consultation (81%)." (PMID 30308700, 2018). "Nevertheless, these BRCA1/2-null cancers develop resistance over time due to restored BRCA1/2 functions, as secondary mutations of BRCA1/2 occur in BRCA1/2-mutated tumors." (PMID 29882812, 2018). "Olaparib (AZD2281) is currently marketed under the trade name of Lynparza and it was approved by FDA for the treatment of homologous recombination (HR)-deficient cancers having BRCA1/2 mutations." (PMID 29374194, 2018). "Other cancers, which have been shown to be associated with BRCA1/2 mutations, include male breast cancer, prostate cancer, pancreatic cancer, and melanoma." (PMID 29662617, 2018). "General practitioners are poorly trained in the management of BRCA1/2‐associated cancer risk, both in terms of initial training and continuing education." (PMID 30308700, 2018). "In fact, predicting sensitivity to PARPi for personalized cancer therapy is difficult and encompasses routine screening for germline pathogenic mutations in BRCA1/2 genes only." (PMID 29465803, 2018). "Among all 33 known oncogenic and suppressive drivers reported in HGSOC29, only BRCA1 expression was associated with cancer morphological diversification." (PMID 30254278, 2018). "Further, BRCA1 methylation loss in carcinomas exposed to chemotherapy underscores the importance of real-time pre-treatment biopsies to assess methylation as a predictor of response to treatment in women with recurrent HGSOC." (PMID 30266954, 2018). "A study has confirmed a role of the FA pathway in supporting the Alt-EJ method of repair in cancers with BRCA1 or BRCA2 deficiencies." (PMID 28239445, 2017). "A successful example of applying the synthetic lethality approach is the targeting of cancers with dysfunction of the breast-cancer susceptibility genes 1 and 2 (BRCA1 and BRCA2) by poly(adenosine diphosphate [ADP]–ribose) polymerase (PARP) inhibitors." (PMID 27880943, 2017). "Women with BRCA1 or BRCA2 gene mutations should undergo annualbreast cancer screening with mammography from age 30onward, as should women who have first-degree relativeswith a proven mutation (category Brecommendation)." (PMID 28894332, 2017). "There is a well-established counseling strategy based on comprehensive mutation-based management guidelines for carriers or families with BRCA1/2 mutations, and patients benefit from early intervention or prevention of cancer." (PMID 28961279, 2017). "In other cancers such as ovarian and breast, mutations in HR genes (e.g., BRCA1/2, ATM) and/or elevated HRD scores (e.g., Myriad Genetics testing scores) predict patient response to PARP inhibitors." (PMID 28212573, 2017).